VIM (vimentin)
Diseases named in the same sentence as VIM in open-access papers (continued):
Sharing a sentence is not in itself a finding about the gene and the disease.
tumor (continued). "Thus, we co-stained tumor samples for E-cadherin and vimentin, as the loss of the former by cancer cells is the main feature of the EMT." (PMID 33214550, 2020). "Furthermore, clinically relevant genes that are associated with tumor growth such as VIM, ITGB1, FOXQ1, FN1, MSN, CXCL and TMPRSS4 were also downregulated." (PMID 32784836, 2020). "Also, we aimed to evaluate the prognostic value of vimentin expression and its association with the tumor immune environment in an mRCC cohort." (PMID 32850341, 2020). "In a recent study, loss of E-cadherin in tumor buds, increased expression of vimentin, and activation of CAFs, all signs consistent with cancer cell EMT, were associated with more aggressive tumors requiring portal vein resection and an increased probability of positive resection margins." (PMID 32466266, 2020). "VIM de-novo expression or overexpression has been reported in various epithelial cancers, including those of prostate, breast and lung, associating with increased tumour growth and invasion." (PMID 32102337, 2020). "Furthermore, the association of tumor budding with vimentin expression supported the idea that EMT is a key process in PDAC responsible for progression and drug resistance." (PMID 31514451, 2019). "Vimentin expression was associated with tumor cell dedifferentiation (p = 0.035)." (PMID 31546725, 2019). "NKp30 recognizes BAT3/BAG6 and B7-H6; NKp44 recognizes NKp44 ligand, a unique splice variant isoform of MLL5 protein; NKp46 recognizes vimentin; and each of these NCRs also recognizes particular heparan sulfate glycosaminoglycans that are uniquely expressed in tumor microenvironments." (PMID 31071196, 2019). "Moreover, it has been reported that increased Vimentin expression was associated with poor prognoses in several different tumor types." (PMID 31761784, 2019). "In addition, a reduction in vimentin levels has also been shown to be associated with tumor cell migration and invasion." (PMID 31569766, 2019). "Epithelial-mesenchymal transition (EMT), which plays an important role in tumor migration, invasion and metastasis, is often characterized by loss of E-cadherin at cell-cell junctions and increased expression of mesenchymal-associated genes such as vimentin." (PMID 30379883, 2018). "The relationship between vimentin and miRs is bi-directional, since vimentin blocks the function of several miRs, including miRs 182, 203, 887, and 3619107, which are proposed to be tumor suppressor molecules that prevent phospholipase D-associated cancer cell migration and invasion." (PMID 30505430, 2018). "Alcohol drinking (P = 0.035) was determined to be a risk factor for DFS, whereas tumor invasive depth (P = 0.066, P = 0.108) and vimentin expression (P = 0.369, P = 0.900), which were significant in Kaplan-Meier analysis, were not identified as prognostic factors in the multivariate model." (PMID 28744307, 2017). "To validate whether the mutated-EGFR promotes vimentin expression, we further conducted immunohistochemistry (IHC) staining on clinical tumor samples." (PMID 28881820, 2017). "Furthermore, we determined the association between L1CAM expression and percentage of vimentin expressing tumor cells, as a marker for EMT." (PMID 29152102, 2017). "That is, given increasing mesenchymal character of the tumor is associated with a poor clinical outcome as well as increasing vimentin and/or decreasing E-cadherin expression; processes associated with these biomarkers should have strong prognostic significance." (PMID 28938541, 2017). "E-cadherin and vimentin are associated with cell motility and tumor metastasis." (PMID 28602785, 2017). "This phenotypic switch including loss of cell contact, upregulation of N-cadherin, Vimentin, Snail, Slug, Twist1 and decreased expression of E-cadherin inversely is important for cell for cancer cells to migrate, invade and induce tumor dissemination from primary site to a secondary organ." (PMID 28032603, 2017).
tumor (continued). "VIM has been shown to increase cell motility, invasion and lamellipodia formation, and its expression is linked to increased metastatic progression, reduced patient survival and poor prognosis across multiple tumor types." (PMID 27259278, 2016). "This was demonstrated by the substantial upregulation of markers typically associated with the mesenchymal phenotype, including fibronectin, vimentin, and N-cadherin, coupled with the loss of epithelial cell contacts mediated by the junction protein E-cadherin in tumor cells resistant to erlotinib." (PMID 27248176, 2016). "A large number of studies have shown the epithelial-mesenchymal transition (EMT) plays a critical important role in tumor cell invasion and metastasis, and leads to upregulation of mesenchymal genes such as Vimentin and downregulation of epithelial-associated markers such as E-cadherin." (PMID 27835885, 2016). "Similarly, MCF-7-LOXL2#12 cells retained their EMT characteristics when cultured in the 3D BME system that models tumor dormancy, depicted by induction of vimentin expression and loss of E-Cad expression." (PMID 27655685, 2016). "Vimentin is a hallmark of primary tumor progression to a metastatic phenotype, which may be involved in the modulation of EMT." (PMID 26824421, 2016). "Elevation of Gal-1 levels in the tumor microenvironment promoted the transition from epithelial cell morphology to the fibroblastoid phenotype, loss of the adherens junction protein E-cadherin and an increase of the mesenchymal marker vimentin." (PMID 27836001, 2016). "Also, decreased levels of vimentin, are associated with decreased migration and invasion of tumor cells." (PMID 27716341, 2016). "Importantly, the expression of Sufu inversely correlated with the expression of miR-214 and vimentin and positively associated with the expression of E-cadherin in the tumor cells from human LAD patients." (PMID 26462018, 2015). "During EMT, tumor cells, which are epithelial-like cells, acquire mesenchymal characteristics, and the loss of the epithelial marker E-cadherin leads to an increase in the mesenchymal markers N-cadherin, fibronectin, and vimentin." (PMID 26440411, 2015). "Moreover, this tumor-related localization was associated with an increased vimentin expression in tumor cells, a higher abundance of myofibroblasts and a higher grading." (PMID 24797069, 2014). "Additionally, EMT has been recognized as a potential mechanism in tumor progression, characterized by the loss or down-regulation of epithelial markers (E-cadherin) and up-regulation of mesenchymal markers (Vimentin)." (PMID 24465741, 2014). "To determine whether deficiency of tuberin in tumor tissue of TSC patients has an effect on vimentin protein expression, we extracted proteins from tumor kidney tissues of TSC patients and normal kidney tissues of healthy subjects." (PMID 25149531, 2014). "From these data, one could speculate that gain of vimentin expression additionally to keratin loss in NSCLC may be a more indicative marker for the development of a more aggressive tumor than keratin loss alone." (PMID 23536778, 2013). "EMT, which is regarded as a critical characteristic of tumor invasion and metastasis is characterized by the loss of epithelial marker E-cadherin and increased expression of mesenchymal markers such as N-cadherin and vimentin." (PMID 23622143, 2013). "Because vimentin expression has been implicated in carcinogenesis, we also examined the expression of this intermediate filament in the different experimental tumor groups." (PMID 23216791, 2012). "Furthermore, the sarcomatoid part of MPNST expresses S100 protein and vimentin, and the tumour is associated with neurofibromatosis type 1." (PMID 23006472, 2012).
tumor (continued). "A highly significant association was observed between GSTPi-positive/vimentin-positive/α-SMA-positive tumour microenvironment-associated stromal fibroblast or CAF at both the primary and metastatic sites in this cohort of patients (Fisher's exact test P<0.001)." (PMID 21897388, 2011). "Cells in the tumor center remain positive for the expression of E-cadherin and cytoplasmic β-catenin, and the tumor cells in the periphery display loss of surface E-cadherin and up-regulation of vimentin as well as nuclear β-catenin staining, the typical characteristics of EMT phenotype." (PMID 21643534, 2011). "In addition, several proteins such as enolase, vimentin, peroxiredoxin 5, Hsp 70, periostin precursor, RhoA, cathepsin D preproprotein, and annexin 1 were found to be associated with the tumor responses to treatment within each subtype." (PMID 22110952, 2011). "Acquired expression of vimentin by carcinoma cells often symbolizes mesenchymal-like cell transformation while loss of E-cadherin or gain of N-cadherin on tumor cell surface is frequently observed in malignant carcinomas and also correlated with enhanced aggressiveness and dedifferentiation." (PMID 20615238, 2010). "The possible association of vimentin with clinically aggressive behaviour of tumours described by others may be explained by the correlation of vimentin expression with lack of steroid receptors and poor differentiation of cancer." (PMID 19695088, 2009). "Vimentin expression in the tumour stroma of CRC was associated with shorter survival." (PMID 17325702, 2007). "We tested whether vimentin expression is associated with these histological characteristics at the tumour–stroma interface." (PMID 17325702, 2007). "Similar to the previous method, circulating tumor cells in peripheral blood from high-risk populations and cancer patients were enriched and identified using a positive sorting method that employed liposome magnetic beads targeting the epithelial cell adhesion molecule (EpCAM) and vimentin." (PMID 40076201, 2025). "In addition, various missense and frameshift mutations identified in Vimentin in human cancers may contribute to the metastatic spread of tumor cells." (PMID 38191501, 2024). "Moreover, reorganization of intermediate filaments, such as vimentin (average log2-fold change 1.23 in WCLs), in tumour cells is associated with epithelial-mesenchymal transition (EMT), promoting migratory and invasive activity of cancer cells of more aggressive phenotypes." (PMID 39462388, 2024). "Of note, elongated VIM+ cells in control tumours may be cancer-associated fibroblasts." (PMID 38238426, 2024). "Although free vimentin in the tumor microenvironment can bind to the surfaces of cancer cells and activate the Wnt signaling pathway, enhancing cellular invasion, the mechanisms underlying vimentin’s translocation to the cell surface remain unclear." (PMID 38685125, 2024). "Moreover, CLSM analysis on PDBCOs confirmed their pathologic origin showing high expression levels of epithelial–mesenchymal transition (EMT) markers, such as vimentin, and proteins associated with tumor aggressiveness and invasiveness, such as TAZ and β-catenin." (PMID 39340087, 2024). "Additionally, this event could be due to the reduced expression of vimentin, evoked by siNDRG1 with TGFβ1 only in these types of cell lines, which is associated with tumor cell invasion and metastasis." (PMID 36594086, 2023). "This analysis showed that MMP14 expression was strongly correlated with that of genes related to stromal cells (including PDGFRB and VIM) as well as that of many collagen genes, suggesting that CAFs might contribute to tumor aggressiveness associated with MMP14." (PMID 36052235, 2022).
tumor (continued). "Considering that EMT of tumour cells plays an essential role in promoting the migration and invasion potentials of tumour cells, we also evaluated the expression level of cell-surface vimentin (CSV), a mesenchymal marker that is known to be associated with a poor prognosis in cancer patients." (PMID 35737211, 2022). "Vimentin is mainly expressed in stromal cells; many researches have revealed that its increased expression was associated with invasive cancer, which could promote the migration and invasion of tumor cells." (PMID 34712728, 2021). "The tumor from patient 1 was diagnosed as a dedifferentiated carcinoma which had apparently undergone epithelial mesenchymal transition leading to the loss of keratin expression and other adhesion molecules such as e-cadherin while expression of vimentin was acquired." (PMID 33087752, 2020). "Indeed, VIM de-novo expression or overexpression has been consistently reported in various epithelial cancers, including those of prostate, breast and lung, associating with increased tumor growth, invasion, poor prognosis, and ultimately, with EMT." (PMID 32758253, 2020). "Rearrangement of vimentin under oxidative stress may also be associated with tumor formation." (PMID 33050149, 2020). "Changingthe growth of the tumor population causes changes inthe expression of epithelial and mesenchymal markers.Thus, the percentage of epithelial markers in MCTSsis less than in monolayer cells; however, spheroid cellsbegin expressing a mesenchymal marker: vimentin." (PMID 30930631, 2019). "Besides, we found that E-cadherin, the loss of which contributed to an EMT process and promoted tumor metastasis, was upregulated and Vimentin and Fibronectin were downregulated after Enah knockdown, which was also reflected by the change of cell morphology and immunofluorescence staining." (PMID 30250066, 2018). "Interestingly, overexpression of p21 in these cells was associated with a reduction of vimentin expression, an observation in agreement with several previous reports on the ability of p21 to inhibit the epithelial–mesenchymal switch in tumor cells." (PMID 29774202, 2018). "Studies conducted in vivo with tumor xenografts of A549 parental and erlotinib-resistant cells demonstrated the sustained overexpression of p-p38 and total p38 kinase, as well as overexpression of the mesenchymal marker vimentin and the EMT-associated transcription factor brachyury." (PMID 27248176, 2016). "Interestingly, Notch2 induction accelerated tumor malignancy along with increased mesenchymal markers, indicating that Notch2 is necessary and sufficient for the loss of E-cadherin and increased N-cadherin and vimentin levels." (PMID 27462787, 2016). "These disregulated genes such as loss of E-cadherin and gain of vimentin have been identified as predictive marker for high-risk HNSCC tumours such as gefitinib resistance, but it remains unclear whether overexpression of EMT-associated genes are directly responsible for gefitinib resistance." (PMID 22315058, 2012). "Observations were made regarding elevated vimentin levels in all types of spheroids derived from MDA-MB-231 tumor cells." (PMID 41597220, 2026). "Western blot also detected an opposite effect with RSPO4 knockdown by siRNAs, including increased levels of N-cadherin, vimentin and fibronectin in tumor cells." (PMID 41522353, 2026). "In vivo studies analyzed tumor tissues for CA IX expression, as well as Vimentin, E-Cadherin, and Caspase-3 levels." (PMID 41823024, 2026). "This transformation is marked by the reduction of E-cadherin and the acquisition of Vimentin and N-cadherin, constituting the fundamental mechanism of tumor cell metastasis." (PMID 41230432, 2026). "Levels of vimentin expression were found to be lowest in homotypic tumor spheroids and heterotypic spheroids (tumor-endothelial cells) derived from MCF7 and SK-BR-3 cells, and highest in MDA-MB-231 cells." (PMID 41597220, 2026).
tumor (continued). "This leads to the suppression of E-cadherin expression and the up-regulation of N-cadherin and vimentin, thereby enhancing the migration and invasion capabilities of tumor cells." (PMID 41141394, 2026). "In all tumors, a heterogeneous expression of PECAM1/CD31 as a marker for vascular components and Vimentin, reflecting the mesenchymal and stromal characteristics of the tumor, was observed." (PMID 40694103, 2026). "An increasing trend of vimentin positivity was seen with increasing tumor size, with positivity in 0 of 3 cases (0.0%) in tumors measuring ≤2 cm, 5 of 28 cases (17.85%) in tumors measuring >2 to ≤5 cm, and 12 of 39 cases (30.76%) in tumors measuring >5 cm." (PMID 42220707, 2026). "FABP4 and vimentin expression was increased in proximity to the tumor, while caveolin-1, CD44, MMP9, and adiponectin showed minimal or no changes." (PMID 41596770, 2026). "Consistent with this, Western blot detected increased level of E-cadherin, reduced levels of vimentin and fibronectin in tumor cells transiently and stably expressing RSPO4 compared with vector control." (PMID 41522353, 2026). "Immunohistochemically, tumor cells showed strong and diffuse cytoplasmic positivity for vimentin, while glial fibrillary acidic protein (GFAP) expression was sparse and showed scattered cytoplasmic positivity in neoplastic cells." (PMID 42038044, 2026). "Our novel inhibitors that selectively block hGIIA's catalysis-independent function slow tumor growth in animal models via interaction with vimentin." (PMID 42232048, 2026). "Immunohistochemically, tumor cells diffusely expressed cytokeratins, vimentin, CD68, CD163, and EMA, with focal expression of SMA, S-100, calponin, and CD3, but were negative for CD21, CD35, CD1a, ALK, and HHV8." (PMID 42311660, 2026). "In vivo, EVs accelerated tumor growth and activated prosurvival (p-AKT, BCL-2), angiogenic (VEGFA, CD31), and epithelial-mesenchymal transition-associated (vimentin) pathways." (PMID 41828681, 2026). "First, we dissected the intensity and distance of tumor invasion by quantitating disseminated human vimentin‐positive tumor cells in the mouse brain parenchyma." (PMID 41181988, 2026). "Protein levels for HBEGF, human tumor cell markers (vimentin), EGFR and astroglial differentiation markers (GFAP, Meteorin) were determined by Western Blot in all treatment groups." (PMID 41181988, 2026). "IL-4 activates the STAT6 pathway, which regulates EMT-related genes, increasing the expression of mesenchymal markers such as vimentin and N-cadherin and supporting tumor cell migration." (PMID 40362280, 2025). "In contrast, both SCC-25 and SCC25-E tumor cells (2 Gy) gained a pEMT profile after irradiation, resulting in high and stable vimentin protein levels." (PMID 40002772, 2025). "Spatial analysis of larger tumor areas confirmed the presence of intratumoral regions characterized by high expression of vimentin in tumor cells and strong infiltration by CD66b+ tumor-associated neutrophils, especially in patients with positive nodal status." (PMID 40155451, 2025). "We demonstrated that the PBRM1/vimentin axis is a critical regulator of tumor grade and metastasis in both mouse and human PDAC." (PMID 40454484, 2025). "By reorganizing the cytoskeleton, vimentin also facilitates the detachment of cancer cells from the primary tumor and their penetration into surrounding tissues." (PMID 39858010, 2025). "The genetic variants were similar to the original tumor tissue, and they owned expression of cancer-associated fibroblast (CAF) markers (FSP1/S100A4, Vimentin) and nuclear translocation β-catenin." (PMID 40299526, 2025). "The vimentin sections showed clear positivity of the tumor tissue for the antibody, as also found in human clinical samples." (PMID 40508127, 2025). "Immunohistochemical (IHC) staining further confirmed the tumor's smooth muscle and mesenchymal origins, with positive for Vimentin, SMA, Syn, Actin, Desmin, and CD34." (PMID 39776317, 2025).